EGFR (epidermal growth factor receptor)
Diseases named in the same sentence as EGFR in open-access papers (continued):
Sharing a sentence is not in itself a finding about the gene and the disease.
cancer (continued). "Notably, the protein targets such as epidermal growth factor receptor (EGFR), mitogen-activated protein kinase 1 (MAPK1) and mitogen-activated protein kinase 3 (MAPK3) were found to maximally participate in >10 cancer pathways." (PMID 40028476, 2025). "Mechanistic studies on HEK293T cells and cancer cell lines (SW480 colon, A549 lung, 5637 bladder) show that the TNS4 SH2 domain interacts with EGFR-phosphorylated c-Cbl, sequestering it away from activated EGFR." (PMID 40906372, 2025). "Molecular targeted therapy has changed the cancer treatment paradigm, with many targeted agents, including ALK tyrosine kinase inhibitor (ALK-TKI) and EGFR tyrosine kinase inhibitor (EGFR-TKI) now standard therapies for patients harboring a corresponding molecular target." (PMID 40833497, 2025). "Inhibiting EGFR, VEGFR, and c-MET, whether by single drugs or drug combinations, has proven beneficial by halting cancer cell growth, proliferation, and metastasis although resistance ultimately develops." (PMID 39920140, 2025). "Additionally, combination treatments targeting EGFR, ERBB2, and downstream PI3K/Akt and Ras pathways have shown downregulation of these cancer targets, along with reduced expression of JAK, STAT, and FAK1." (PMID 41024300, 2025). "Specifically, we focused on four previously-studied, targeted anti-cancer drugs for which our model includes primary targets and significant off-targets: trametinib (MEK inhibitor), alpelisib (PI-3Kα inhibitor), neratinib (EGFR/ErbB2/ErbB4 inhibitor), and palbociclib (CDK4/6 inhibitor)." (PMID 40880521, 2025). "This approach may provide deeper insights into the dynamics of EGFR signaling and the role of SMARCB1 in modulating this cancer pathway." (PMID 39971779, 2025). "Concomitantly, proliferative cascades such as EGFR, PI3K, and MAPK were uniformly downregulated, which is consistent with reports describing TRIM28 as a positive regulator of cell cycle progression and growth factor–mediated proliferation in various cancers." (PMID 41303350, 2025). "Epidermal growth factor receptor (EGFR) is a transmembrane glycoprotein belonging to the ERBB family of receptor tyrosine kinases (RTKs), which controls a variety of biological processes in cancer." (PMID 40523886, 2025). "It is widely used in cancers such as non-small cell lung cancer and pancreatic cancer and could be relevant in OCS cases with demonstrated EGFR overexpression." (PMID 40336633, 2025). "Notably, prior studies have demonstrated that B7-H3 enhances the EGFR–extracellular signal-regulated kinase (ERK) signaling pathway, promoting cancer cell growth, metastasis, and chemoresistance." (PMID 40004194, 2025). "AhR can activate EGFR through both traditional genomic signaling and nongenomic pathways, promoting cancer cell proliferation and resistance to EGFR–TKIs by activating proto-oncogene tyrosine-protein kinase Src (Src) signaling." (PMID 39578555, 2025). "Illustration of a biological pathway involving FMD, EGFR-TKI, and cancer cells." (PMID 40808689, 2025). "Cancer cells including HCC are characterized by overexpression of receptor tyrosine kinases (RTKs) such as epidermal growth factor receptor (EGFR) and vascular endothelial growth factor receptor (VEGFR) that control cell proliferation and angiogenesis in cancer cells." (PMID 40076329, 2025). "The response to EGFR TKIs is universally linked to the presence of EGFR mutations in the tyrosine kinase domain (TKD), irrespective of the cancer’s primary histology." (PMID 40364160, 2025). "CMTM4 KD reduced activation of EGFR/Akt/mTOR and NF-κB pathways, suggesting that different CMTM family members may have distinctly different functions in cancer cells." (PMID 39948411, 2025).
cancer (continued). "In contrast, in NSCLC, a report suggests that IFIT3 might, however, act to promote cancer progression via its upregulation by COL8A1 and subsequent mediation of EGFR activation, a major factor in pathogenesis of this disease." (PMID 40564154, 2025). "Notable exosomal proteins, such as the epidermal growth factor receptor (EGFR) and epithelial cell adhesion molecule (EpCAM), play significant roles in cancer progression through mechanisms including angiogenesis, proliferation, metastasis, and treatment resistance." (PMID 40317075, 2025). "Erlotinib, an EGFR-TKI, also has the potential to induce OS in cancer cells by upregulating NOX-4." (PMID 40563358, 2025). "The concurrent downregulation of VEGFR2, EGFR, and mTOR by 4-TCPA may create a multi-pronged attack on cancer cell survival and proliferation pathways." (PMID 40592982, 2025). "By synthesizing current insights on both RTK and non-RTK mediated resistance against anti-EGFR therapies, this review aims to guide future research and improve therapeutic strategies for these cancers." (PMID 40560045, 2025). "Coordinated targeting of EGFR via CBD and TKIs could represent a logical approach for cancer treatment, particularly in HNSCC, where CBD receptors and EGFR signaling pathways interact." (PMID 40864738, 2025). "There are also antibodies on nanoparticle platforms such as Au-NPs and IO-NPs used to bind to certain receptors on the cell surface of cancer cells like HER2 and EGFR, which then carry treatment options including chemotherapy or CRISPR therapy to the cancer cells." (PMID 40688030, 2025). "HOTAIR, a LncRNA that serves as a therapeutic target in various types of cancer, has been silenced through an EGFR-targeting aptamer conjugated to a HOTAIR-specific siRNA, leading to a reduced viability, migration, and invasion of EGFR-positive TNBC cells." (PMID 41181715, 2025). "Molecular docking studies revealed that the newly designed compounds exhibited better binding affinities (−7.2 to −9.8 kcal/mol) to key cancer-related targets (CDK2, EGFR, and Tubulin) compared to the reference drug and the most active molecule (molecule 39) in the dataset." (PMID 40526618, 2025). "In response to anti-EGFR therapy resistance, HER2 (Human Epidermal Growth Factor Receptor) therapy was developed (amplified and/or overexpressed ERBB2/HER2 triggered constant signals for cell division and survival, driving cancer progression)." (PMID 41465541, 2025). "This highlights the need for a nuanced understanding of EGFR signaling in different contexts and the development of therapeutic strategies that can modulate its activity to promote healing without compromising cancer treatment outcomes." (PMID 40564048, 2025). "The Cancer Genome Atlas and other studies have identified HRAS, CASP8, and NOTCH1 mutations in human papillomavirus-negative, EGFR-negative HNSCC." (PMID 41463200, 2025). "It is now well accepted that resistance to anti-EGFR therapies arises from both cell-autonomous mechanisms and non-cell-autonomous interactions between cancer cells and TME." (PMID 40362183, 2025). "In an interesting observation, while employing DepMap, we noted that several cancer cells that were sensitive to osimertinib had a negative score for agrin in addition to phosphorylated EGFR." (PMID 40165020, 2025). "We found 6 significant gene-cancer type pairs impacted by CNAs where samples also contained eccDNA copies of the gene, including PIK3CA in BRCA, KRAS in COAD and LUAD, BRAF in SKCM, and EGFR in LUAD." (PMID 41415395, 2025). "EGFR/HER2 and TGF‐β pathways can cooperate with each other in EMT and cancer progression." (PMID 40859866, 2025).
cancer (continued). "Curcumin could reverse multidrug resistance in cancer cells by inhibiting the function or expression of proteins such as P-gp, BCRP, multidrug resistance-related protein (MRP), and EGFR." (PMID 40490812, 2025). "Four genes (DCC, EGFR, LRIG3, and RUNX1) mutated in GTKO-F0 pig No. 681 were previously found to be mutated in some human cancers." (PMID 40833781, 2025). "Consequently, there is a growing interest in formulating novel techniques that facilitate the concurrent use of MET and EGFR inhibitors, particularly in instances when MET serves as a targetable co-driver, such as in EGFR-mutant cancers." (PMID 40881676, 2025). "For example, polymeric nanoparticle-based treatments, engineered to target the epidermal growth factor receptor (EGFR), which is often overexpressed in NSCLC, deliver therapeutic agents directly to cancer cells, enhancing efficacy while minimizing side effects." (PMID 40386463, 2025). "Similarly, OC combined with lapatinib synergistically inhibited the growth of HER2-positive cancer cells and suppressed the activation of HER2, EGFR, and c-MET pathways." (PMID 40002421, 2025). "The combinations include EGFR inhibitor, IGF1-R/IR inhibitor, Akt inhibitor, and mTOR inhibitor that can directly or indirectly target different components of the PI3K/Akt/mTOR pathway a crucial signaling cascade in several cancers." (PMID 41427337, 2025). "This comparison highlights the distinct glycosylation patterns between receptor EGFR and its ligand DCN, which may have implications for their functional interactions and roles in cancer biology." (PMID 40285620, 2025). "Receptor Tyrosine Kinases (RTKs), such as EGFR and VEGFR, are often overactive in cancer cells." (PMID 41180630, 2025). "Upregulated TET1 acts as an oncogene, leading to the hypomethylation and activation of cancer‐specific oncogenic signaling pathways (including phosphoinositide 3‐kinase [PI3K], epidermal growth factor receptor [EGFR], and platelet‐derived growth factor), which results in the development of TNBC." (PMID 40599235, 2025). "Core nodes include IL6, MYC, VEGFA, EGFR, and ESR1, all of which play essential roles in cancer development and may act as critical molecular regulatory hubs." (PMID 40045358, 2025). "For example, metabolites such as butyrate and ursodeoxycholic acid have been shown to finely tune EGFR, VEGF, and PI3K/AKT/mTOR signaling—cascades central to both cancer biology and muscle metabolism—thereby modulating cellular energy flux, inflammatory responses, and tissue-repair processes." (PMID 41568005, 2025). "A similar mechanism may exist in EGFR-TKI resistance, where upregulated TNNC1 may promote cancer cell survival by enhancing autophagic flux, thereby conferring resistance to EGFR-TKIs such as erlotinib." (PMID 40433361, 2025). "Anoikis resistance, essential for cancer metastasis, is promoted in cancer stem cells (CSCs) by elevated ITGA2 and ITGB1 expression, which interact with EGFR to activate the ERK/Akt survival pathway, enabling CSCs to evade cell death in the absence of extracellular matrix." (PMID 41008552, 2025). "In addition to this, the compound 24f with a cyanophenyl substitution showed dual inhibition of EGFR with IC50 = 4.34 μM and HER2 with IC50 = 2.28 μM, which are the key targets in cancer therapy." (PMID 41488515, 2025). "EGFR, MET, and AKT signaling is important for cancer cell survival." (PMID 40920675, 2025). "Although EGFR is expressed in many cancers, it does not comprehensively cover all refractory cancers." (PMID 39751657, 2025). "Of note, although SBS22a appears to be mostly clonal, EGFR and other major cancer driver genes in the Taiwanese samples are not enriched with the typical T:A>A:T mutation patterns of SBS22a." (PMID 40161734, 2025). "Although these studies have highlighted the critical role of TKI-induced EGFR ubiquitination, the intricate molecular mechanisms governing EGFR ubiquitination and deubiquitination in TKI-treated cancer cells remain unclear." (PMID 40168312, 2025).
cancer (continued). "Based on network pharmacology and molecular docking predictions identifying EGFR/STAT3 signaling as a potential key mechanism, we investigated whether curcumin modulates this pathway to affect cancer cell proliferation, apoptosis, invasion, and migration." (PMID 41312415, 2025). "Moreover, NSD3 can directly monomethylate EGFR at K721 in the tyrosine kinase domain to activate EGFR-ERK signaling and promote cell cycle progression in this cancer." (PMID 41301842, 2025). "Notably, both EGFR and TRIB3 are involved in the MAPK pathway, which plays a pivotal role in cancer development." (PMID 40104395, 2025). "EGFR mutant NSCLC tumors evade macrophage phagocytosis via activating the AKT/NF‐κB and ERK/c‐Myc signaling pathways to increase CD47 expression, which acts as a signal of “don't eat me,” preventing macrophages from phagocytosing cancer cells." (PMID 40859900, 2025). "Cu activates important cancer signaling pathways like 3-phosphoinositide-dependent protein kinase 1 (PDK1), phosphoinositide-3-kinase/Akt pathway, and epidermal growth factor receptor (EGFR) pathway." (PMID 41198664, 2025). "The data further suggested an under‐activation in the EGFR and JAK–STAT signaling pathways, which might indicate a predominantly PI3K/mTOR‐driven cancer phenotype for this patient, further supporting the rationale for mTOR inhibition." (PMID 39876058, 2025). "The results demonstrated that EGFR.Sig was negatively correlated with the infiltration of various immune-promoting cells, including CD8+ T cells, NK cells and macrophages, in different cancer types." (PMID 40574864, 2025). "For patients whose cancer does not express the EGFR antigen, it is necessary to find another structure that NIR-PIT can specifically target." (PMID 40574027, 2025). "Treatment with BMA is recommended not only for the prevention and/or treatment of SRE, but also to improve survival, particularly in cancers with typically poor post-bone metastasis survival such as GI cancer and NSCLC without the EGFR mutation." (PMID 39851958, 2025). "The ERBB signaling pathway, mediated by ERBB receptor tyrosine kinases (ERBB-1/EGFR, ERBB-2/HER2, ERBB-3, and ERBB-4), is crucial for cellular proliferation, survival, migration, and angiogenesis, which leads to cancer progression." (PMID 40901642, 2025). "Historically, long-term attempts to use chemically synthesized inhibitors of the epidermal growth factor receptor (EGFR), including fourth-generation drugs, in the fight against cancer have not been successful." (PMID 40700134, 2025). "Given its dual role as both an EGFR modulator and downstream effector in Ras/Raf/Mek/MAPK signaling, combinatorial targeting of TNS4 and EGFR represents a rational strategy for EGFR-dysregulated cancers." (PMID 40906372, 2025). "The primary focus will be on the mechanisms behind anti-EGFR resistance, which can arise from both RTKs and non-RTKs in both cancer types." (PMID 40560045, 2025). "The platform’s ability to degrade both the EGFR/HER2 and the PD-L1/VISTA pairs highlights its versatility and superior degradation efficiency, paving the way for future applications in dual-target inhibition and cancer therapy." (PMID 41038820, 2025). "Thus, both the status of MIG6 expression and ERFFI1 mutations could serve as additional biomarkers, alongside well‐established EGFR mutation status, to select patients who may benefit from EGFR‐targeted cancer therapy, particularly in cases where known oncogenic EGFR mutations are absent." (PMID 39129344, 2025). "Finally, we obtained a regulatory network of 38 nodes with a wide range of connections, which reflected the universal and close relationship of Hub-EGFR.Sig and ICD in the immune response of pan-cancer." (PMID 40574864, 2025). "Notably, the epidermal growth factor receptor (EGFR) is a prime example, where a strong correlation exists between EGFR-driven cancers and increased HIF-1α levels across various cancer types, even under normoxic conditions." (PMID 39470609, 2025).